VEGFA (vascular endothelial growth factor A)
Diseases named in the same sentence as VEGFA in open-access papers (continued):
Sharing a sentence is not in itself a finding about the gene and the disease.
tumor (continued). "VEGFA and HMGA2 have both been reported to be dysregulated and promoted tumor progression in various cancers." (PMID 30755600, 2019). "Further in vivo studies showed that anlotinib inhibited tumor growth, induced autophagy and suppressed JAK2/STAT3/VEGFA pathway, and CQ enhanced this effect." (PMID 30755242, 2019). "Our results showed that tumor hypoxia at molecular level was relatively high at early stage of tumor development as reflected by initially high HIF1A and VEGFA expression levels and their subsequent decrease." (PMID 30412628, 2018). "miR-153 can inhibit both the HIF1α/VEGFA and ANG1/Tie2 pathways to suppress tumor growth and angiogenesis." (PMID 29959560, 2018). "The knockdown of XBP1 in TNBC cells caused a significant reduction in the expression of HIF1α target genes, such as vascular endothelial growth factor A (VEGFA), a key mediator of tumour angiogenesis." (PMID 30248920, 2018). "Mounting research has shown that many tumours secrete a diversity of angiogenic factors (such as VEGFA, PDGFB, bFGF and EGF) to promote tumour angiogenesis." (PMID 30584257, 2018). "Some of these genes, including GDF15, TGM2, VEGFA and ZNF385A were also up-regulated in primary tumor cells from patient 32 after co-culture with N-MSCs." (PMID 29503225, 2018). "Overexpression of miR-299 significantly suppressed spheroid-based tumor-induced formation of blood vessels in vitro and tumor growth in vivo, while knockdown of TUG1 decreased the expression level of VEGFA, a molecular switch of tumor angiogenesis." (PMID 30217088, 2018). "Among several identified factors secreted by tumors, vascular endothelial growth factor A (VEGFA), placental growth factor, transforming growth factor β (TGF-β), and tumor necrosis factor (TNF) were first demonstrated to prepare “soil” for tumor cells." (PMID 30061895, 2018). "Bevacizumab is a humanized monoclonal antibody against vascular endothelial growth factor A (VEGF), a key angiogenic promoter in tumours." (PMID 30135261, 2018). "Cancer cells are known to secrete pro-angiogenic signals such as vascular endothelial growth factor A (VEGFA) and induce an angiogenic-switch by engaging the tumor microenvironment." (PMID 30046396, 2018). "To investigate the potential role of VEGFA in SIRT2-mediated tumour angiogenesis, we evaluated the migratory ability of HUVECs incubated with CM from ShSIRT2 SW480 cells and stimulated with VEGFA." (PMID 30584257, 2018). "Once tumor cells and macrophages arrived at vessels, macrophages in TMEM secreted VEGFA to regulate vascular permeability transiently and assisted tumor cell intravasation." (PMID 29599778, 2018). "We also monitored the expression level of tumor cell-secreted LOX, MMP-2 and VEGFA, and the bone marrow-derived CD11b+ cell number in the distant organs in the in vivo model." (PMID 29848296, 2018). "Although the angiogenic effect of VEGFA is predominantly mediated by VEGFR2, VEGFR1 signaling plays a role in tumor cell survival and growth." (PMID 29670046, 2018). "When VEGFA is blocked, the ANG1/Tie2 pathway is thought to be the major contributor to tumor angiogenesis and tumor growth." (PMID 29959560, 2018). "Western blotting of the xenograft tumour tissues from the nude mouse model showed that overexpression of ABHD11‐AS1 increased the expression of cyclin D1, CDK1, CDK2, CDK4, Bcl‐xl and VEGFA and decreased the expression of p16." (PMID 29799152, 2018). "Previous research has implicated TAFs in recruitment of pro-angiogenic immune cells promoting tumor angiogenesis via a mechanism mediated by matrix metalloproteinase MMP9 and VEGFA." (PMID 29921235, 2018). "Herein, we identify RASAL2 as a novel tumor suppressor in RCC, and it can inhibit RCC angiogenesis via p-GSK3β/c-FOS/VEGFA pathway." (PMID 30158581, 2018). "Macrophages can be recruited by CSF1 and other tumor chemoattractants such as CCL2, VEGFA, and semaphoring 3A (SEMA3A) in developing TME." (PMID 30220913, 2018).
tumor (continued). "As for angiogenesis process, miR-218 overexpression significantly suppressed the protein levels of VEGFA and ANGPT2 in SW620 and HCT116, which play important role in tumor angiogenesis." (PMID 29977158, 2018). "A diversity of angiogenic factors (such as VEGFA, PDGFB, bFGF and EGF) secreted from tumour cells have been reported to play an important role in tumour angiogenesis." (PMID 30584257, 2018). "Recent studies have also implicated the tumor-fibroblast interactions in tumor angiogenesis by increasing expression in tumor cells of MMP9 and pro-angiogenic growth factors such as VEGFA and HB-EGF." (PMID 29921235, 2018). "Antiangiogenic therapy (AAT) targets the VEGFA/VEGFR2 axis to inhibit recruitment of tumor vasculature and aid in tumor regression." (PMID 30158456, 2018). "Antiangiogenic treatments targeting the vascular endothelial growth factor A (VEGF-A) pathway have been shown to improve blood supply and oxygenation in some preclinical tumor models, and to reduce blood supply and induce hypoxia in others." (PMID 28606060, 2017). "In vivo, we found that increased NOTCH1 signalling in tumour xenografts led to increased expression of endothelial FABP4 that decreased when NOTCH1 and VEGFA inhibitors were used in combination." (PMID 27568980, 2017). "Arguably, the most well-studied HIF target gene is the angiogenic/permeability vascular endothelial growth factor A (VEGF-A), which is expressed in both tumor and stromal cells." (PMID 29136509, 2017). "Bcl2, VEGFA, PTEN, Jun, Fos, APC2 were up-regulated and Ccna2, Cdc25a, Mcm3, Mcm6, Ccnb2, Mcm5, Cdk1, Gadd45a, Myc were down-regulated in MMQ tumor stem-like cells group." (PMID 28163656, 2017). "Many genes can promote the secretion of VEGFA in cancer cells by controlling FAK expression or activity, then activates FAK pathway in endothelial cells, resulting tumor angiogenesis." (PMID 28415713, 2017). "VEGFA is anchored by Fibronectin in the extracellular matrix, and then soluble VEGFA is released from matrix by metalloprotease MMP9 produced by tumor or infiltrating myeloid cells via TAK1 signaling." (PMID 28977919, 2017). "VEGFA stimulated sphere formation only in the ALDH1+ subpopulation and increased OVCA‐initiating cells and tumor formation in vivo through Bmi1." (PMID 28179359, 2017). "One of the most interesting observations of the current study was that VEGFA had a distinct pattern of expression in MMQ tumor stem-like cells and was further validated in tumor spheres of human prolactinoma." (PMID 28163656, 2017). "Many genes account for several aspects of the endothelial response, such as VEGFA, IL6 and TYMP for tumor angiogenesis, and S1PR1 for development and cell differentiation." (PMID 29088816, 2017). "To further investigate the mechanisms responsible for the tumor-suppressive abilities of miR-29c, we searched TargetScan, MICRORNA.ORG and MIRDB and verified that VEGFA is a potential target of miR-29c." (PMID 28241836, 2017). "This study demonstrates that miR-29c plays a tumor-suppressive role in LAD and its function is mainly mediated by its target-VEGFA." (PMID 28241836, 2017). "This shows that tumour endothelial FABP4 expression is induced by activation of NOTCH1 signalling, and can be targeted by inhibition of VEGFA and NOTCH1 signalling." (PMID 27568980, 2017). "VEGFA blockade, by interrupting angiogenesis, creates tumor hypoxia, which would stimulate HIF‐1α‐dependent VEGFA induction to stimulate hypoxia‐tolerant, chemoresistant stem‐like cells to reseed local and metastatic niches." (PMID 28179359, 2017).
tumor (continued). "It is also important to note that in addition to tumor cells, macrophages and, to a lesser extent, tumor infiltrating lymphocytes (TIL), represent major sources of VEGFA, and macrophage-produced VEGFA has been shown to promote tumor angiogenesis and invasion." (PMID 28403223, 2017). "In pathway in cancer and cell cycle, Bcl2, VEGFA, PTEN, Jun, Fos, APC2 were up-regulated and Ccna2, Cdc25a, Mcm3, Mcm6, Ccnb2, Mcm5, Cdk1, Gadd45a, Myc were down-regulated in the MMQ tumor stem-like cells." (PMID 28163656, 2017). "The reduction of miR-9-5p, miR-144, miR-145 and miR-229 leads to tumor progression through the miR-9-5p/POU2F1, miR-144/c-Met, miR-145/ZEB2 and miR-229/VEGFA signaling pathway." (PMID 28548946, 2017). "Active VEGFA, IL8 and HBEGF then stimulate tumor vasculature acting upon endothelial cells or pericytes." (PMID 28977919, 2017). "Two of these drugs, Cixutumumab and Bevacizumab, each target a single gene that controls important biological processes for tumor progression: cellular proliferation by inhibiting IGF1R and vascularization by inhibiting VEGFA, respectively." (PMID 29152063, 2017). "Several previous studies demonstrated that genomic alterations such as VEGFA or FGF3/4 amplification can identify HCC patients who showed clinical responses after sorafenib treatment, although tumor biopsy specimens are required." (PMID 29258450, 2017). "VEGFA mRNA expression decreased 43.7 and 33.9% in MMQ tumor stem-like cells and MMQ cells by siRNA silencing compared with siControl transfected cells, respectively." (PMID 28163656, 2017). "Although our results demonstrate ADAM9 proteins regulate VEGFA and ANGPT2 expression regardless protease activity, shedding function of ADAM9 is still important for pro-angiogenic factors generation to promote tumor growth." (PMID 29118335, 2017). "Here, we show that VEGFA mediates stem cell actions in primary human OVCA culture and OVCA lines via VEGFR2‐dependent Src activation to upregulate Bmi1, tumor spheres, and ALDH1 activity." (PMID 28179359, 2017). "To address the efficacy of VEGFA on MMQ tumor stem-like cells, we down-regulated the expression of VEGFA in MMQ cells and MMQ tumor stem-like cells by small interfering RNAs." (PMID 28163656, 2017). "Thus, TUG1 regulation could alter VEGFA level, which in turn affects tumor angiogenesis." (PMID 27362796, 2016). "Another example is TUG1-hsa-miR-34a- VEGFA, which is a competing triplet that involved in the KIRC tumor state." (PMID 27580177, 2016). "We found that the combination of anti-VEGFA and anti-CCL2 yielded better suppression efficiency on tumor growth, angiogenesis, TAMs accumulation, and lung metastasis than either single antibody application." (PMID 27541266, 2016). "We further demonstrated the anti-angiogenic capacity of quininib by examining gene expression of angiogenic factors in xenograft tumours and found that the expression of IL6, IL8, NRP2, VEGFA and FGF1 was reduced by quininib treatment." (PMID 27739445, 2016). "HSCs in active state also produce soluble factors favoring tumor growth, such as hepatocyte growth factor and TGF-β, and proangiogenic factors such as vascular endothelial growth factor-A (VEGF-A) and MMP9." (PMID 29259674, 2016). "The VEGFA and CCL2 mainly released by fibroblasts in the tumor microenvironment are responsible for tumor angiogenesis and TAMs accumulation, thereby boosting tumor growth and metastasis." (PMID 27541266, 2016). "Previous studies showed that in addition of factors like VEGFA and bFGF, which promote tumor angiogenesis, myelomonocytic cells also produce EGF, HGF, MMP-9 and other cytokines that directly enhance the tumor cell survival, growth and invasion." (PMID 27391260, 2016). "The expressions of vascular endothelial growth factor-A (VEGF-A) and CD31 (an endothelial cell marker) were decreased significantly in tumor tissues of mice treated with HEGU." (PMID 27314329, 2016).
tumor (continued). "Dopamine also reduces VEGFA-induced mobilization of bone marrow CD45-CD34+VEGFR2+ cells to peripheral blood and results in restrained tumor growth." (PMID 26799933, 2016). "Dual blocking of VEGF and FGF2 has been achieved with the use of a fusion protein containing peptides of both VEGFA and FGF2, this fusion protein was used to vaccinate tumour bearing mice." (PMID 26620208, 2016). "One UPR, the pro-angiogenic factor VEGFA, was activated by CPA treatment in GL261 tumors but was uniquely inhibited in LLC tumors, as was validated by analysis of CPA effects on LLC tumor microvessel density." (PMID 27515027, 2016). "The positive correlation between the same hypoxia gene signature and HIF-1α, VEGFA and SLC2A1 suggests that the imaging parameters reveal real functional aspects reflecting the oxygen status in the tumor." (PMID 27634881, 2016). "In GBM and other cancers, pro-angiogenic signaling molecules, including basic fibroblast growth factor (bFGF) and vascular endothelial growth factor A (VEGF-A), are secreted by stromal cells and tumor cells." (PMID 27270311, 2016). "More importantly, we demonstrated that systemic delivery of anti-VEGFA/CCL2 or pre-miR-1, pre-miR-206 and anti-miR-31 dramatically decreased tumor angiogenesis, TAMs accumulation, tumor growth and lung metastasis." (PMID 27541266, 2016). "HIF-2α is pivotal in promoting tumor aggressiveness and angiogenesis by trans-activating its downstream genes, including GLUT-1 and VEGFA." (PMID 26943772, 2016). "Gliomas have been shown to express high levels of TGF-β, VEGFA, HGF, and Sema3a, which promote tumor growth, neo-vascularization, invasiveness, and dispersal." (PMID 26755653, 2016). "miR-17-92 and miR-192 inhibited the progression of cancers via suppressing tumour angiogenesis through targeting multiple tumour angiogenesis-inducing genes, TGFBR2 (transforming growth factor, beta receptor 2), HIF1α and VEGFA in vivo and in vitro." (PMID 27213336, 2016). "We found gene expression value of VEGFA and SLC2A1 in the tumor component to be significantly positively correlated to stromal HIF-1α." (PMID 27634881, 2016). "I.p. delivery of anti-CCL2, anti-VEGFA and anti-CCL2/VEGFA combination dramatically reduced lung tumor growth, angiogenesis, TAMs accumulation, and tumor metastasis in mice." (PMID 27541266, 2016). "As an example, tumor-promoting macrophages are recruited to tumor cells by chemotactic factors including CCL2, VEGFA, and M-CSF." (PMID 26000250, 2015). "VEGF family members, including VEGFA, VEGFB, VEGFC, and VEGFD, are secreted by autocrine stimulation of tumor cells as well as through paracrine influences of the proangiogenic tumour microenvironment." (PMID 25810565, 2015). "A distinctive expression profile of VEGFA, EFNB2, PECAM1/CD31, ANGPT1 and ANGPT2 was revealed: VEGFA, EFNB2, and ANGPT2 were found overexpressed in 84 % to 95 % of tumour samples." (PMID 26044849, 2015). "Malignant tumors express vascular endothelial growth factor A (VEGF-A), a glycoprotein that recruits blood vessels, thereby supplying tumors with the oxygen and nutrients that promote tumor cell migration, proliferation, survival, permeability, and metastasis." (PMID 26209534, 2015). "VEGFA, PKIB and TMPRSS2 were increased by FGF23 stimulation in LNCaP cells while the tumor suppressor TXNIP was decreased." (PMID 26019137, 2015). "HIF-1α is a master regulator of tumor angiogenesis, and SHARP1 inhibited VEGFA mRNA expression in our study." (PMID 24918449, 2014). "Forinstance, miR-125a, which is always significantly downregulated in HCC, inhibits themetastasis of tumor cells by targeting MMP11 and vascular endothelial growth factor A(VEGF-A)." (PMID 25012758, 2014). "For example, suppression of major angiogenic regulators like VEGFA (conventionally referred to as VEGF), or release of endogenous anti-angiogenic factors like endostatin or thrombospondin can be used to inhibit tumor angiogenesis." (PMID 25329517, 2014).
tumor (continued). "Previous studies have shown that NRP-1 acts as a co-receptor for VEGFR-2/VEGFA, and NRP-1 mediates a VEGFA/NRP-1/VEGFR-2 pathway, leading to tumor angiogenesis." (PMID 25333267, 2014). "Constitutively activated STAT3 has been reported to upregulate VEGFA expression and thereby induce tumor angiogenesis; phosphorylated Src thus aggravates BBB leakage following ischemia through the upregulation of VEGFA expression." (PMID 25269821, 2014). "More specifically, tumor-promoting target genes, e.g. MMP7/9, IL-8 and VEGFA, were synergistically upregulated, while intriguingly negative modulators of HH/GLI signaling, such as HHIP and PTCH1, were downregulated." (PMID 23762360, 2013). "The VEGF/VEGFR pathway is a key mediator of angiogenesis and VEGFA acts as a potent tumor angiogenic factor." (PMID 23536895, 2013). "Vascular endothelial growth factor A has also been shown to work synergistically with CXCL12, a chemokine commonly expressed by tumors, to promote tumor angiogenesis." (PMID 23874342, 2013). "Over-expression of VEGFA activates the VEGFR pathway, promoting the proliferation, migration, and survival of endothelial cells, resulting in the formation of tumor blood vessels." (PMID 24287492, 2013). "Conversely, a high-level synergism was also observed, due to a strong and significant upregulation of numerous canonical EGF-targets with putative tumor-promoting properties such as MMP7, VEGFA, and IL-8." (PMID 23762360, 2013). "In the case of VEGFA, SEMA5A, and SEMA3G, the expression levels in the MSL subtype were closer to those of normal tissues than the tumor average." (PMID 23667446, 2013). "In the classical signal transduction pathway of VEGFA in promoting angiogenesis, GRN is involved in three kinase pathways that regulate tumor growth (MAPK, P13K, and FAK)." (PMID 24349832, 2013). "Further studies showed that JXY suppressed the vascular endothelial growth factor A (VEGF-A) expression and its receptor 2 (VEGFR-2) among the HCC HepG2 cells, HUVECs, and tumor." (PMID 23956767, 2013). "When the oxygen level drops vascular endothelial growth factor-A (VEGFA, also denoted vascular permeability factor) will be secreted from the tumor cells." (PMID 24213317, 2012). "VEGFA, a growth factor and MMP2, a cellular matrix protein, involved in tumor formation and metastasis are found repressed by Pax6." (PMID 23056534, 2012). "We demonstrated that genotyping of rs699947 (VEGFA, AC) and rs2269772 (ITGA, AA) have an independent role in determining the metastatic site of gastric cancer cells even when tumour histology is included in the analysis." (PMID 22808003, 2012). "Bevacizumab (trade name, AVASTIN®, Genentech/Roche), a monoclonal antibody raised against human vascular endothelial growth factor A (VEGFA) inhibits the VEGFA signaling pathway, which is involved in tumor-derived angiogenesis." (PMID 23206527, 2012). "Bevacizumab, a humanized monoclonal antibody to vascular endothelial growth factor-A (VEGF-A), was originally developed as an anti-tumor treatment." (PMID 23077404, 2012). "We noticed that VEGFA, HIF1A, SOX4, SOX9, MMP2, TGFB1 genes are overexpressed together with S6K1 in all 4 tumour types investigated." (PMID 22570651, 2012). "The anti-angiogenic (CXCL9, CXCL10) and pro-angiogenic markers (VEGFa, CXCL2, CXCL5, Angiopoietin 1 and Angiopoietin 2) were quantified in the tumor by RTQPCR." (PMID 22815789, 2012). "Avastin, developed by Genentech/Roche, has a slightly different mechanism in that it blocks to process of angiogenesis by binding to vascular endothelial growth factor A (VEGF-A), a chemical signal over-produced by tumor cells." (PMID 24212948, 2011). "In the VEGFA165 tumours mouse-specific VEGFR2 mRNA was twofold upregulated (P=0.001), the main receptor for VEGFA signalling." (PMID 22045186, 2011). "Vascular endothelial growth factor A (VEGFR-1) and Flk-1/KDR (VEGFR-2) are key regulators for tumor angiogenesis and tumor growth." (PMID 21808639, 2011).